SNAI2 (snail family transcriptional repressor 2)
Diseases named in the same sentence as SNAI2 in open-access papers (continued):
Sharing a sentence is not in itself a finding about the gene and the disease.
cleft palate (1 paper, 2013). Cleft palate is a fissure type embryopathy that affects the soft and hard palate to varying degrees. "We have found that on the C57BL/6J background virtually all Snai2-lacZ/Snai2-lacZ homozygotes now die in the early postnatal period, apparently as an increase in the penetrance of the cleft palate phenotype." (PMID 24270643, 2013).
diffuse large B-cell lymphoma (1 paper, 2023). "It is worth noting that the only type of SNAI2 gene alteration in Lymphoid Neoplasm Diffuse Large B-cell Lymphoma (DLBCL) and MESO cases was deep deletion." (PMID 37251370, 2023).
endometrioid adenocarcinoma (1 paper, 2016). An adenocarcinoma characterized by the presence of malignant glandular epithelial cells resembling endometrial cells. "EMT program plays important roles in promoting tumor cell invasion and chemoresistance of endometrioid adenocarcinoma cells via several transcription factors and related pathways, such as SNAIL (SNAI1), and SLUG (SNAI2)." (PMID 27601936, 2016).
endometrioid endometrial carcinoma (1 paper, 2020). "When compared with the normal endometrium, SNAI1 was upregulated as early as in the noninvasive (stage 1A) and myoinvasive (stage 1B) tumors, followed by the expression of TWIST1, ZEB1, and SNAI2 in the myoinvasive (stage 1C) tumors of endometrioid endometrial carcinoma." (PMID 32370157, 2020).
endothelial dysfunction (1 paper, 2025). In vascular diseases, endothelial dysfunction is a systemic pathological state of the endothelium (the inner lining of blood vessels) and can be broadly defined as an imbalance between vasodilating and vasoconstricting substances produced by (or acting on) the endothelium. "The expression of the genes encoding EndoMT transcription factors (SNAI1, SNAI2, TWIST1, and ZEB1), which are generally upregulated at endothelial dysfunction, also showed ≥2-fold increase after PA-BSA treatment, in particular the TWIST1 (≈eight-fold increase) and SNAI1 genes (≈four-fold increase)." (PMID 41465574, 2025).
enteritis (1 paper, 2024). Inflammation of the small intestine. "Several studies have shown that Snai2 expression is upregulated in enteritis, which is consistent with our findings." (PMID 38646621, 2024).
ependymoma (1 paper, 2022). A WHO grade II, slow growing tumor of children and young adults, usually located intraventricularly. "Specifically, in RELA fusion-type ST ependymomas, there is an upregulation of N-cadherin mRNA levels, along with SNAI1/Snail, SNAI2/Slug, and ZEB1, which are genes related to the EMT and downregulation of E-cadherin." (PMID 36291193, 2022).
ganglioglioma (1 paper, 2010). A well differentiated, slow growing neuroepithelial neoplasm composed of neoplastic, mature ganglion cells and neoplastic glial cells. "Mean SNAI2/Slug mRNA expression was low in non-tumor brain (112 ± 42) and in gangliogliomas (119 ± 52), which have low invasive potential." (PMID 20565806, 2010).
gastrointestinal stromal tumor (1 paper, 2019). "This study aims to investigate the upstream miRNAs of SNAI2 and their influence on the metastasis of gastrointestinal stromal tumors (GISTs)." (PMID 31749661, 2019).
heart failure (1 paper, 2020). Inability of the heart to pump blood at an adequate rate to meet tissue metabolic requirements. "The expression of most of the pro-fibrotic and EndoMT mediating genes like CTGF, SNAI1, SNAI2, Twist 1 and 2, BMP4, and Actn1 are upregulated during heart failure and most of these are down-regulated at Week 19 (recovery)." (PMID 33584806, 2020).
ischemic stroke (1 paper, 2021). A stroke disorder caused by obstruction of blood flow to the brain, due to thrombotic (local blood clot formation) or embolic (due to a blood clot or other material traveling from another site) event. "Although the regulation of miR-429 on the cells has been confirmed, SNAI2 played a key role in the progression of ischemic stroke." (PMID 34966442, 2021).
Lowe syndrome (1 paper, 2021). "In summary, our data suggest that upregulation of SNAI2 and possibly partial EMT could contribute to the progressive kidney phenotype observed in Lowe syndrome and Dent II disease; however, confirmation of these results in animal model systems and Lowe syndrome/Dent II disease patients is necessary." (PMID 34069732, 2021).
malaria (1 paper, 2023). Malaria is a serious and sometimes fatal disease caused by a parasite that commonly infects a certain type of mosquito which feeds on humans. "SNAI2 is another multi-function protein with a differential pattern of transcription in our co-culture experiments, with roles in several areas associated with malaria disease, including apoptosis and signalling (Wnt; Notch)." (PMID 38033133, 2023).
malignant peripheral nerve sheath tumor (1 paper, 2019). Malignant peripheral nerve sheath tumor (MPNST) is a rare and often aggressive soft tissue sarcoma occurring in a wide range of anatomical sites. "EMT-associated transcription factors such as SNAIL (SNAI1), SLUG (SNAI2), Twist Family BHLH Transcription Factor (TWIST)-1, Zinc Finger E-Box Binding Homeobox (ZEB) have been shown to be upregulated in malignant peripheral nerve sheath tumor (MPNST) deficient for neurofibromin." (PMID 30967630, 2019).
pancreatic adenocarcinoma (1 paper, 2019). "Normalized mRNA expression data from TCGA studies of breast, prostate, lung, colorectal and pancreatic adenocarcinomas was downloaded for ZEB1, ZEB2, SNAI1, SNAI2, TWIST1, FOXQ1 and FOXC218,19." (PMID 31780722, 2019).
Pancytopenia (1 paper, 2023). An abnormal reduction in numbers of all blood cell types (red blood cells, white blood cells, and platelets). "Snai2 KO mice showed increased sensitivity to DNA damage induced by irradiation and all Snai2 KO mice died by day 13 post irradiation due to severe pancytopenia." (PMID 37600794, 2023).
prostate disease (1 paper, 2019). "Additional genes identified as affected transgenerationally in this study have also been previously associated with prostate disease including Fli1, Egf, Dgk2 and Snai2." (PMID 30778168, 2019). "Several genes previously associated with prostate disease were also identified as affected in the current study: Fli1 (stromal DMR), Egf (epithelial DMR), Dgk2 (stromal differentially expressed mRNA), Snai2 and Cxcl1 (epithelial differentially expressed mRNA)." (PMID 30778168, 2019).
psoriasis (1 paper, 2015). An autoimmune condition characterized by red, well-delineated plaques with silvery scales that are usually on the extensor surfaces and scalp. "Consistent with these trends, psoriasis-specific and non-specific DEGPs were oppositely regulated by RNA interference treatments targeting pro- and anti-differentiation genes, respectively (e.g., SNAI2, ANCR, STAU, ZNF750)." (PMID 26251673, 2015).
Rb (1 paper, 2022). "In this study, advanced Rb tumors showed increased expression of EMT signatures (ZEB1, FC = 92, p < 0.05; SNAI2, FC = 5.57, p < 0.05), which was a consequence of miR-181a-5p downregulation, as an EMT trigger." (PMID 36291907, 2022). "However, ZEB1 (FC = 77.2, p < 0.05), SNAI2 (FC = 3.32, p < 0.05), ABCB1 (FC = 4.4, p < 0.05), and CTSL (FC = −3.8, p < 0.05) expressions were significantly downregulated in non-advanced Rb tumors." (PMID 36291907, 2022).
scleroderma (1 paper, 2023). Scleroderma is a rare autoimmune connective tissue disorder characterized by abnormal hardening of the skin and, sometimes, other organs. "Thus, combined approaches that target both the SNAI2 and the VDR signaling systems may be more effective in treating high grade malignant cancers and possibly skin disorders involving fibrosis such as scleroderma." (PMID 37228489, 2023).
serous ovarian tumors (1 paper, 2021). "Our study identified the expression and role of SNAI2 in serous ovarian tumors, indicating the progression of serous ovarian tumors possibly through EMT." (PMID 34440070, 2021).
Stroke (1 paper, 2024). Sudden impairment of blood flow to a part of the brain due to occlusion or rupture of an artery to the brain. "Key EMT-related genes that were downregulated upon MMP-3 KO in male stroke brains included Fbn1, Fbln1, Tgfb1, Tgfbr3, Snai2, and Fgf2." (PMID 39000490, 2024). "We also observed sex-specific alterations in other EndMT-associated genes; male MMP-3 KO stroke brains showed downregulation of Tgfbr3 and the major EMT-associated transcription factor Snai2." (PMID 39000490, 2024). "Key EMT-related genes that were downregulated in MMP-3 KO males included Fbn1, Fbln1, Tgfb1, Tgfbr3, Snai2, and Fgf2, while female MMP-3 KO stroke brains showed downregulation of Fbln5, Fbln1, Fbln2, and Tgfb1." (PMID 39000490, 2024).
Testicular atrophy (1 paper, 2013). Wasting (atrophy) of the testicle (the male gonad) manifested by a decrease in size and potentially by a loss of fertility. "In contrast, single germline deletions of either Snai2 or Snai3 are viable although Snai2 deficient males are described as having decreased fertility due to testicular atrophy." (PMID 23874916, 2013).
uterine corpus endometrial carcinoma (1 paper, 2022). A endometrial carcinoma (disease) that involves the body of uterus. "High SNAI2 expression was significantly correlated with worse OS in most cancer types—except uterine corpus endometrial carcinoma, in which low SNAI2 was correlated with worse OS." (PMID 34792282, 2022).
vascular malformation (1 paper, 2023). A non-neoplastic disorder that is the result of defects of vascular morphogenesis. "Future studies aimed at blocking SNAI2 or other EMT-inducing transcription factors could reveal the role of this process in the pathogenesis of complex lymphatic anomalies and other vascular malformations." (PMID 37842094, 2023).
viral infection (1 paper, 2024). "SNAI1 is a direct target of IRF3, and viral infection as well as intracellular Poly I:C treatment have been shown to induce SNAI1 and SNAI2 expression." (PMID 39159817, 2024).
tumor (445 papers, 2006 to 2026). "Third, we found that the expression level of SNAI2 is associated with tumor immunity, but the specific mechanism of action is still unclear and needs to be further explored." (PMID 37251370, 2023). "From the results of the tumor-associated genes analysis, the most significant ten tumor- associated genes such as SNAI2, VCAM, MMP2, BRCA1, PARP1 and MECOM were closely associated with UCPs." (PMID 35090503, 2022). "SNAI2 KD caused a significant reduction in the tumor size, weight and volume compared to control shScr." (PMID 33420019, 2021). "Unexpectedly, tolerance to therapy appears to be the default state, with treatment response correlating with the prevalence of tumor cells deficient for SNAI2, a key regulator of EMT reprogramming." (PMID 34322653, 2021). "Snai2 is associated with tumor development and aggressiveness by changing the gene expression of E-cadherin and VIM, and functions as a direct inhibitor of E-cadherin by targeting the specific E-boxes of the E-cadherin proximal promoter." (PMID 33085646, 2020). "According to our results, specific changes in the protein expression of VEGFR3/FLT4, HGFR/MET, and SLUG/SNAI2 were associated with the EMP-like phenotype of tumor cells." (PMID 32899940, 2020). "The methylation of the SNAI2 gene negatively associated with higher tumour grade (grade 3) (OR = 0.61; 95% CI, 0.39–0.97; P = 0.038) and higher grade positively associated with the high Ki-67 proliferative index (OR = 17.34; 95% CI, 2.89–103.88; P = 0.002)." (PMID 30189837, 2018). "Expression of proteins that are characteristic of mesenchymal cells (e.g. vimentin, FSP1/S100A4, SNAI1, SNAI2, and stromelysin-3) and loss of epithelial markers (e.g. E-cadherin) correlates with tumor progression and poor prognosis." (PMID 21966391, 2011). "The SNAI1 and SNAI2 genes have been implicated in tumor progression and metastasis, and both were recently shown to be direct transcriptional target of ATF3 in human mammary cells." (PMID 21304988, 2011). "The varied amounts of SNAI2 expression in various tumor types could indicate different underlying functions and processes." (PMID 37251370, 2023). "In addition, we tried to screen out the targeting SNAI2-binding proteins We combined the TCGA tumor expression data with the GEPIA2 program to find the top 100 genes that are linked with SNAI2 expression." (PMID 37251370, 2023). "Therefore, the abnormal expression of SNAI2 in tumor tissue cannot currently be associated with genetic alteration." (PMID 37251370, 2023). "Taken together, tumor cells undergoing EMT with elevated SNAI2 expression and hypoxia scores may have caused genomic instability." (PMID 37377752, 2023). "The cause of SNAI2 overexpression in tumor metastasis remains largely unclear." (PMID 36457025, 2022). "In particular, we hypothesize that SNAI2 deficiency in pretreatment tumor cells render them susceptible to cell death induced by AR signaling inhibition." (PMID 34322653, 2021). "Cells expressing high level of SNAI2 are deficient in tumor-initiating ability." (PMID 27760172, 2016). "As SNAI2 protein is implicated in e.g. cancer invasion and metastasis, the nIGF-1R-mediated effects shown in this study may influence such important tumor phenotypic actions." (PMID 27275536, 2016). "To ascertain the role of SNAI2 in TPM cancers in promoting tumor cell survival, we used siRNA and overexpression approaches, coupled with measuring apoptosis." (PMID 40560846, 2025).
tumor (continued). "High NQO1 expression, localized to SNAI2+/CDH1low/CDH2high cells at the invasive front, facing the tumor stroma, is consistent with recent findings that NQO1 supports a sustained EMT response by stabilizing Snail transcriptional activity." (PMID 40600748, 2025). "SNAI2 can play important roles in tumor aggressiveness, possibly by recruiting chromatin regulators for epigenetic silencing." (PMID 40560846, 2025). "Nonetheless, it should be highlighted that the behavior of SNAI2 seems to disappear on the primary tumor cells and be re-expressed in the metastatic and stromal-derived cells." (PMID 40332096, 2025). "In the primary tumor, NQO expression was largely confined to the tumor cells facing the stroma, similar to the distribution for Ki67 and SNAI2 expression." (PMID 40600748, 2025). "CCL26high OSCC had a characteristic of tumor invasive phenotype with upregulated CLDN8/20 and reduced keratin KRT36, which was significantly associated with EMT markers (CDH1, CDH2, VIM, SNAI2)." (PMID 39931245, 2025). "CDH1 was downregulated when the TP was compared with N, while SNAI2 was downregulated in all tumour regions." (PMID 40869272, 2025). "SNAI2 is recognized as a transcription factor associated with EMT and is crucial in tumor metastasis." (PMID 41356226, 2025). "In all four TPM tumor lines tested, knockdown of SNAI2 using 50 pmol siRNA for 72 h led to a marked increase in apoptosis as measured by CC3 and cleaved PARP (CP)." (PMID 40560846, 2025). "A heatmap analysis was conducted using a TCGA dataset of LUAD patients for TNFAIP6, PLK1, and mesenchymal markers including CDH2, SNAI1, and SNAI2 in paired normal tissue (left, normal) and adjacent tumor tissues (right, LUAD) depending on stages." (PMID 40860188, 2025). "Accordingly, target genes of c-Myc (such as Cst1, Snai2 and Bcl2) related to tumor invasion, metastasis, and drug resistance were upregulated in Panc1 cells with NLS-TLR3 rescue, compared with other two groups." (PMID 40675966, 2025). "N‐cadherin/CDH2, a key EMT biomarker and effector, was enriched in primary tumor cells that showed upregulation of SNAI2 and diminished expression of E‐cadherin." (PMID 40600748, 2025). "Abnormal expression of SNAI2 in tumor tissue correlates with low differentiation, recurrence, metastasis, and poor prognosis." (PMID 38702792, 2024). "miR-133b suppresses SF3B4, affecting downstream molecules, such as KLF4, KIP1, and SNAI2, potentially inhibiting tumor metastasis." (PMID 39273339, 2024). "The results indicated that overexpression of SNAI2 significantly promoted tumor growth, while knockdown of USP7 markedly inhibited tumor growth." (PMID 38702792, 2024). "The subcutaneous stromal plug model in nude mice confirmed the role of SNAI2 in USP7-mediated tumor VM in vivo." (PMID 38702792, 2024). "Our study found that the expression of SNAI2 is increased in RMS tissues and is associated with clinical features such as tumor stage and metastasis." (PMID 38702792, 2024). "It has been shown that the transcription factor SNAI2 in glioma gives the tumor cells an ability to metastasize into multi-organs." (PMID 36770654, 2023). "We discovered heterogeneity in SNAI2 expression in different tumor tissues and cancer cell lines by exploring public datasets." (PMID 37251370, 2023). "The negative feedback balance between the tumor suppressor breast cancer gene 1 (BRCA1) and the transcription factor SNAI2 gene (Slug) is a key element to maintaining normal tumor growth and determining TME’s stem cell concentration." (PMID 36672697, 2023). "The SNAI2-overexpressing cells inhibited cell growth, tumorsphere formation, tumor growth, enhanced sensitivity to cisplatin, reduced stem cell-related factors’ expression, and lowered tumor initiating frequency." (PMID 36674577, 2023). "Tumor latency was monitored after injection of SiHa-Vec and SiHa-SNAI2 cells into the NOD/SCID mice." (PMID 36674577, 2023).